STAT3 (signal transducer and activator of transcription 3)
Diseases named in the same sentence as STAT3 in open-access papers (continued):
Sharing a sentence is not in itself a finding about the gene and the disease.
breast cancer (continued). "Another recent study reported that C3G attenuates breast cancer angiogenesis by inhibiting the STAT3/VEGF pathway." (PMID 37132754, 2023). "Pyrimethamine, which is a STAT3 antagonist, has chemotherapeutic and immune-stimulatory effects in breast cancer models in mice." (PMID 37710280, 2023). "Our results identified the IL-6/STAT3 signaling pathway as an important therapeutic target in breast cancer radiotherapy." (PMID 36635302, 2023). "Our data demonstrate that upon TME Stimulation, STAT3 had opposing roles in regulating pro-tumor activities in HR+/HER2− breast cancer cells." (PMID 37190183, 2023). "TLR4, as a receptor of resistin, which has high expression in human breast cancer, also mediates the promoting effect of resistin on epithelial-to-mesenchymal transition and stemness in breast cancer, combined with the downstream NF-κB/STAT3 pathway." (PMID 37576399, 2023). "Through activating crucial genes related to breast cancer stem cells, STAT3 contributes to breast cancer metastasis and therapeutic resistance." (PMID 37642779, 2023). "HMGB3 inhibition inhibits colony formation and induces apoptosis by increasing reactive oxygen species accumulation and decreasing MMP, p-mTOR, and STAT3 levels in human breast cancer cells." (PMID 37328851, 2023). "STAT3 has been found to be constitutively activated in a high proportion of all breast cancer subtypes." (PMID 37834225, 2023). "The activation of STING-regulated IL-6/STAT3 increases the expression of PD-1 ligand in breast cancer." (PMID 37051596, 2023). "Together, these findings demonstrate that PRRG4 increases mtDNA content and promotes mitochondrial function through activation of STAT3 in breast cancer cells." (PMID 38102641, 2023). "For example, targeting the SH2 domain of STAT3 with a novel small molecule decreased the percentage of breast cancer tumor-initiating cells as well as mammo sphere formation." (PMID 37720284, 2023). "IL-6 and p-STAT3 levels correlated with a poor radiotherapy response in patients with breast cancer." (PMID 36635302, 2023). "and Thomson have been studied extensively, and various chemicals such as crispenes C, D, F, and G showed cytotoxicity against STAT3-dependent MDA-MB 231 breast cancer cells." (PMID 38138272, 2023). "A role for STAT3 in facilitating invasion and metastases has also been identified using mouse models of breast cancer." (PMID 37199043, 2023). "IHC was carried out to analyze the levels of IL-6 and p-STAT3 in a cohort of 103 patients with breast cancer." (PMID 36635302, 2023). "The dysregulation of the STAT3 signaling pathway is frequently observed in breast cancer and contributes to tumor progression." (PMID 37569363, 2023). "Activation of STAT3 signaling by IL-11 in breast cancer was recently reported to promote tumor invasion and metastasis." (PMID 37153732, 2023). "STAT3 activation is frequently observed in breast cancer cells, and inhibiting STAT3 using siRNA offers a promising approach for inhibiting human tumor cells." (PMID 37242674, 2023). "Taken together, our results indicate that STAT3 mediates PRRG4-induced POLG expression in breast cancer cells." (PMID 38102641, 2023). "MK138 and MK150, the two most potent derivatives of Tilfrinib, selectively inhibit PTK6 and suppress STAT3 activity in T47D breast cancer cell lines." (PMID 37509364, 2023). "Further, in vivo studies revealed that the growth of STAT3 siRNA transfected MDA-MB-231 breast cancer cells was significantly lower than in control mice and was associated with an increased number of apoptotic cells in the tumor site." (PMID 38067351, 2023). "Our study uncovers that PRRG4 via Src-STAT3 regulates POLG expression by increasing the transcription of POLG in breast cancer cells." (PMID 38102641, 2023). "The continuous activation of the IL-6/STAT3 signaling pathway has been detected in cell proliferation, survival, and invasion of many human cancers, including breast cancer." (PMID 37298475, 2023).
breast cancer (continued). "SDC1 is capable of modulating breast cancer stem cell phenotypes via interleukin (IL)-6/signal transducers and activators of transcription 3 (STAT3), Notch, and epidermal growth factor receptor (EGFR) signaling pathways." (PMID 36980680, 2023). "In vivo studies revealed that the intravenous administration of STAT3 siRNA and paclitaxel-carrying particles to breast cancer-bearing mice significantly reduced tumor growth and metastasis compared to treating the mice with each agent separately." (PMID 38067351, 2023). "Another work has unveiled a FUT8 regulatory axis in breast cancer based on the transcription factor activator protein 2γ (AP-2γ) binding to the Signal Transducer and Activator of Transcription 3 (STAT3)." (PMID 36980181, 2023). "We have used Stat3 and Src as proof of principle that intelligent targeting of breast cancer cells prior to the development of endocrine resistance can be advantageous and enhance drug sensitivity." (PMID 36266450, 2023). "This oncometabolite contributes to a lower pH and promotes cell proliferation, in which additional lactate is reported to induce M2 macrophage polarization via the ERK/STAT3 signaling pathway in breast cancer or MCT-HIF1α signaling in gastric cancer." (PMID 36986884, 2023). "LIF expression in these cells is increased as a result of signal transducer and activator of transcription 3 (STAT3) activation by CXCL1 from breast cancer cells." (PMID 37108425, 2023). "When co-cultured with breast cancer cells, the adipose tissue induced EMT and increased the invasiveness of the breast cancer cells in a STAT3 dependent manner." (PMID 37841259, 2023). "Recent data indicate that overexpressed and constitutively activated STAT3 is involved in the development, tumour-promoting inflammation, progression, and chemoresistance of breast cancer." (PMID 37298475, 2023). "In sum, our study unveils the pivotal biological role of PRMT6-mediated STAT3 R729me2a in breast cancer metastasis and underscores the prospective utility of PRMT6 inhibitors as effective therapeutic strategies against STAT3-driven metastatic breast cancer." (PMID 37813837, 2023). "Mechanistically, CD96 enhances mitochondrial fatty acid β‐oxidation via the CD155‐CD96‐Src‐Stat3‐Opa1 pathway, which subsequently promotes chemoresistance in breast cancer stem cells." (PMID 36581470, 2023). "C3G can provide effective protection against the adverse effects of ultraviolet B radiation, by regulating the MAPK and NF-κB signaling pathways, and can also inhibit breast cancer angiogenesis, by inhibiting the STAT3 pathway." (PMID 36677726, 2023). "Autocrine IL-6 signaling, which proceeds via the JAK/STAT3 pathway, is known to promote breast cancer proliferation, survival, migration, and invasiveness." (PMID 38250802, 2023). "It has been previously reported that CD44 can promote CSC traits of metastatic breast cancers by activating the PDGFRβ/Stat3 signaling pathway." (PMID 37117249, 2023). "The GPX8/IL-6/STAT3 axis has been shown to maintain an aggressive breast cancer phenotype, and GPX8 itself mediates the proliferation and migration of GBM cells." (PMID 37795080, 2023). "In breast cancer, the activation of signal transducer and activator of transcription 3 (STAT3) has been reported to significantly increase the transcription of MEK5." (PMID 37601096, 2023). "Blockade of STAT3 using various techniques sensitized breast cancer cells (MDA-MB435) to apoptosis induced by taxol and adriamycin (doxorubicin) chemotherapy." (PMID 38026933, 2023). "Both transcription factors are directly phosphorylated by PTK6 and STAT3, when activated, promotes proliferation and migration and impairs apoptosis in colon cancer cell lines, mouse models, and breast cancer cell lines MDA-MB-231 and T47D." (PMID 37509364, 2023).
breast cancer (continued). "STAT3, a typical oncoprotein that promotes chemo-resistant phenotype formation in breast cancers, is activated to a greater extent through tyrosine 705 residue phosphorylation in MCF7/T and MX-1/T cells." (PMID 37242532, 2023). "The biological activity of the compounds was tested by toxicity assay on three STAT3 N-domain-dependent cell lines, breast cancer MDA-MB-231, and prostate cancer PC-3 and DU145." (PMID 37182134, 2023). "In this study, we showed that CAF-derived IL-6 induced STAT3 activation, which promoted breast cancer cell growth and radioresistance." (PMID 36635302, 2023). "In breast cancer cells, circRHOT1 functions by adsorbing miR-106a-5p, which targets STAT3 in this cell type." (PMID 37332354, 2023). "It played a critical role in different stages of cancer progression and was essential for transduction of IL6-class inflammatory cytokine signaling; it was also involved in mediation of the oncogenic activation of STAT3 in mammary cancer cells." (PMID 37895906, 2023). "STAT3 is known to be one of the most important transcriptional factors regulating the expression of key oncogenes involved in breast cancer." (PMID 37298475, 2023). "For example, contrary to normal fibroblasts, cancer associated fibroblasts (CAFs) release high levels of IL-6 and CCL2 upon STAT3 activation in co-cultured breast cancer cells,promoting the stem cell renewal and atmosphere forming capacity." (PMID 37720284, 2023). "Hyperactivation of STAT3 is well documented in multiple cancers, including hepatocellular carcinoma, multiple myeloma, leukemia, breast cancer, and so on." (PMID 38017510, 2023). "In the current study, we investigated the tumor suppressive role of EHF, which is thought to inhibit migration and invasion through the induction of senescence and the inhibition of the STAT3 signaling pathway in breast cancer cells." (PMID 37958443, 2023). "In light of their well-described pro-metastatic roles in other aspects of malignancy in breast cancer, these findings call for the careful consideration of the therapeutic effects of inhibitors targeting STAT3 and p65 in the clinic." (PMID 37190183, 2023). "The aim of this study was to establish a prognostic role for IL6/JAK/STAT3 signalling pathway members in a larger retrospective cohort of breast cancer patients (n = 850) with a focus on TNBC." (PMID 37199043, 2023). "As previously illustrated that MSC℗ decrease breast cancer cell growth and sensitize cancer cells to radiotherapy by downregulating the signal transducer and activator of transcription 3 (STAT3) signaling pathway." (PMID 38213319, 2023). "Recent studies indicate that targeting PIM1 significantly suppresses breast cancer metastasis as well as the PIM1/STAT3 axis." (PMID 36982538, 2023). "Patients with breast cancer-related bone metastasis exhibit increased serum levels and mRNA expression of IL-11, suggesting that IL-11 is involved in bone metastasis via STAT3 phosphorylation." (PMID 37199584, 2023). "First, EGCG was reported to inhibit adipocyte/cancer cell STAT3-mediated oncogenic paracrine control, thereby preventing adipogenesis and the obesogenic environment that favors breast cancer development." (PMID 36670988, 2023). "STAT3 regulates the progress of breast cancer and the proliferation of cells by targeting oncogenes." (PMID 37374977, 2023). "A study found that STAT3-mediated IL-10 secretion can promote the formation of M2 macrophages, and M2 macrophages regulate the function of breast cancer stem cells through EGFR/STAT3/SOX-2 paracrine signals." (PMID 36911202, 2023). "C3G can inhibit breast cancer angiogenesis through the STAT3 signaling pathway; however, C3G’s inhibition of human GC cells remains elusive in terms of its specific molecular mechanism." (PMID 36677726, 2023). "It was reported that MDSCs strongly induce STAT3 phosphorylation in breast cancer cell lines like MCF-7 and MDA-MB-231 co-cultured with MDSCs." (PMID 38090567, 2023).
breast cancer (continued). "Our results reveal that PRRG4 promotes migration and invasion of breast cancer cells by modulating mitochondrial function through the Src-STAT3-POLG axis." (PMID 38102641, 2023). "IL6/JAK/STAT3 signalling is upregulated in breast cancer; however, there is limited evidence for its role in TNBC." (PMID 37199043, 2023). "For example, the interaction between MRTFA and STAT3 promotes the migration of breast cancer cells, and the crosstalk of MRTF-YAP is required for cancer cell migration and metastasis." (PMID 37982489, 2023). "There is limited evidence in the literature to date which explores IL6/JAK/STAT3 as prognostic or predictive biomarkers in breast cancer." (PMID 37199043, 2023). "IL-6-induced p-STAT1 and p-STAT3 were lower in naïve CD4+ T cells from breast cancer patients compared to healthy donors." (PMID 37741983, 2023). "ZSW also decreases the mammosphere formation of breast cancer stem cells (BCSCs) by inhibiting STAT3." (PMID 37173892, 2023). "IL-11 is essential for promoting osteolysis in breast cancer bone metastasis via RANKL-independent osteoclastogenesis by activating the JAK1/STAT3 signaling pathway." (PMID 37199584, 2023). "Calcium signaling functions extensively in many cellular processes and calcium signaling promotes the progression of several cancer types such as glioma, prostate cancer and breast cancer by activating STAT3, an important transcription factor in cancer." (PMID 37055846, 2023). "PR39/STAT3 siRNA complexes entered the 4T1 breast cancer cells, which resulted in the effective silencing of STAT3." (PMID 38067351, 2023). "In fact, it has been well characterized as downstream of the STAT3 signaling pathway, which leads to the accumulation of breast cancer stem cells and increases the likelihood of tumor recurrence or metastasis." (PMID 37056339, 2023). "ACA potently inhibited osteolysis in a mouse breast cancer skeletal metastasis model through the SHP-1/STAT3/MMPs signaling pathway." (PMID 38203502, 2023). "STAT3 also plays a key role in breast cancer by acting as a transcriptional activator, regulating several target oncogenes and affecting breast cancer progression, proliferation, apoptosis, metastasis, and chemoresistance." (PMID 37368660, 2023). "Another study revealed that the IL-6 receptor gp130 is present in breast cancer cell-derived EVs and stimulates STAT3 signaling in BMDMs." (PMID 36670988, 2023). "CircRHOT1 notably inhibits ferroptosis and the levels of ROS, iron in breast cancer cells through sponging miR-106a-5p, which targets the signal transducer and activator of transcription 3 (STAT3)." (PMID 37065473, 2023). "In this study, we revealed that AURKA inhibitor MLN8237 upregulated the expression of PD-L1 in breast cancer by increasing the level of p-STAT3 and impeding the infiltration of CD3+ T and CD8+ T cells in tumor tissues, thus impaired antitumor immune response." (PMID 37781397, 2023). "Another G4 aptamer, namely T40231 [G2T(G3T)2G3], directly targets STAT3 protein and dramatically reduces tumor cell growth by markedly enhancing the apoptosis of prostate and breast cancer cells in which STAT3 is constitutively activated." (PMID 37298475, 2023). "VEGF raised the expression level of c-MYC by activating STAT3 and enhances the self-renewal of breast cancer stem cells." (PMID 36721232, 2023). "Osteopontin-a upregulates the levels of glucose in breast cancer cells through STAT3, likely via its transcriptional targets apolipoprotein D and IGFBP5." (PMID 38039408, 2023). "A synthetic anti-gp130 compound (bazedoxifene) inhibited IL-6-induced growth of breast cancer cell lines and down-regulated STAT3 phosphorylation." (PMID 36835413, 2023). "There was an increased STAT3 activation in HER2-positive breast cancer cells that was related to the stem-like potential of these cells." (PMID 38067351, 2023). "They demonstrated that compounds 38 and 39 strongly inhibited Stat3 signaling in four human prostate and breast cancer cell lines." (PMID 38069175, 2023).
breast cancer (continued). "Another study also demonstrated the existence of the positive feedback mechanism between the lactic acid production and HIF-1α/STAT3 axis to promote tamoxifen‐resistant breast cancer cells." (PMID 37900137, 2023). "Using this hybrid, the treatment of nude mice bearing human MCF-7 breast cancer cells led to suppression of p-STAT3 and a decrease in Ki-67 immunostaining in the tumor tissues." (PMID 37376060, 2023). "Recombinant IL-6 significantly enhanced the level of p-STAT3 and resulted in increased clone numbers of breast cancer cells in a concentration dependent manner." (PMID 36635302, 2023). "Given that STAT3 promotes breast cancer metastasis, it is also a potential target of breast cancer treatment." (PMID 37781397, 2023). "For example, the curcumin analogs FLLL31 and FLLL32 demonstrate a potent ability to inhibit STAT3 phosphorylation and thus suppress tumor growth in breast cancer by interfering with the DNA-binding domain of STAT3 and initiating apoptosis." (PMID 37173951, 2023). "The in vitro and in vivo data strongly indicated that activated STAT3 is a critical anti-apoptotic factor in breast cancer." (PMID 38067351, 2023). "From a clinical perspective, we unearthed the promising potential of STAT3 R729me2a as a robust prognostic marker for predicting the overall survival time of breast cancer patients." (PMID 37813837, 2023). "The results showed that the expression of SLC31A1 was significantly positively correlated with immune markers in breast cancer, especially for STAT3 of Th17 (r = 0.382, p < 0.001), STAT1 of Th1 (r = 0.358, p < 0.001), and CCR8 of Treg (r = 0.304, p < 0.001)." (PMID 37275369, 2023). "To assess the effect of VaM on STAT3 in breast cancer, we evaluated the phosphorylation status of STAT3 and its upstream regulator, Src." (PMID 37569363, 2023). "Herein, we found that CAF-secreted IL-6 activated the STAT3 signaling pathway to promote breast cancer cell growth and radioresistance." (PMID 36635302, 2023). "In breast cancer, IL-6 is found to be overexpressed and has been described as a tumor-promoting cytokine through its major effector STAT3." (PMID 36835413, 2023). "The abnormal activation of STAT3 has been shown to be closely related to chemotherapy resistance in bladder cancer, blood cancer, glioma, ovarian cancer, breast cancer and acute myeloid leukemia." (PMID 38031104, 2023). "The observed inhibition of cell proliferation in this HER2-overexpressing in breast cancer was related to a caspase-dependent extrinsic apoptotic mechanism and suppression of the STAT3/VEGF signalling pathway." (PMID 37375922, 2023). "Induced by the cytokine IL-6, functional roles for Stat3 in inducing breast cancer growth and driving breast cancer metastasis have recently been reported." (PMID 36266450, 2023). "As a CBSI, S-72 inhibits STAT3 tyrosine phosphorylation in both paclitaxel-sensitive and resistant breast cancer cells." (PMID 37242532, 2023). "This retrospective study has demonstrated a prognostic role for JAK/STAT3 signalling in breast cancer with potentiation in TNBC." (PMID 37199043, 2023). "For instance, it has been demonstrated that IL-6, secreted by adipocytes, is able to induce epithelial–mesenchymal transition, enrichment of cancer stem cells, and resistance to PI3K inhibitors via STAT3 activation in ER-expressing MCF-7 breast cancer cells." (PMID 37834225, 2023). "The last drug hit was Sertindole which exhibits antiproliferative activities in breast cancer with a potential application for the treatment of breast-to-brain metastases and by inhibiting the STAT3 signaling pathway in human gastric cancer cells." (PMID 37993971, 2023). "In breast cancer, senile neutrophils produce exosome piR-17,560 in a STAT3-dependent manner, which binds to FTO and increases ZEB1 expression by reducing m6A methylation, promoting chemotherapy resistance and EMT in BC cells." (PMID 38031146, 2023).